NDRG4 (NDRG family member 4)
Description:
Contributes to the maintenance of intracerebral BDNF levels within the normal range, which is necessary for the preservation of spatial learning and the resistance to neuronal cell death caused by ischemic stress (By similarity). May enhance growth factor-induced ERK1 and ERK2 phosphorylation, including that induced by PDGF and FGF. May attenuate NGF-promoted ELK1 phosphorylation in a microtubule-dependent manner.
Synonyms: SMAP-8; BDM1; KIAA1180; SMAP8
Tractability: Antibody: its Gene Ontology location is reachable by antibodies, with high confidence. PROTAC: its protein half-life has been measured.
Gene: Protein-coding gene on chromosome 16 (58,462,846 to 58,513,628, forward strand). Ensembl gene ENSG00000103034.
Subcellular location: Cytoplasm, cytosol
Subcellular location (Human Protein Atlas): Cytosol; Plasma membrane
Gene Ontology:
Molecular function: protein binding
Biological process: negative regulation of platelet-derived growth factor receptor signaling pathway; negative regulation of smooth muscle cell migration; negative regulation of smooth muscle cell proliferation; positive regulation of ERK1 and ERK2 cascade; cardiac muscle cell proliferation; cell differentiation; clustering of voltage-gated sodium channels; embryonic heart tube development; heart looping; positive regulation of neuron projection development; signal transduction; cell migration involved in heart development; positive regulation of extracellular matrix assembly; regulation of endocytic recycling; visual learning
Cellular component: basolateral plasma membrane; cytoplasm; cytosol; endoplasmic reticulum membrane; cell projection membrane; membrane
Genetic constraint (gnomAD): Loss-of-function variants: 34 observed, 55.35 expected, observed/expected ratio (o/e) 0.61, 90% interval 0.47 to 0.82. The upper end of that interval is the gene's LOEUF score, 0.82, which puts it in group 3 of 6, group 1 being the genes least tolerant of losing a copy. Missense variants: 408 observed, 438.17 expected, observed/expected ratio (o/e) 0.93, 90% interval 0.86 to 1.01. Synonymous variants: 175 observed, 173.39 expected, observed/expected ratio (o/e) 1.01, 90% interval 0.89 to 1.14.
Homologues: Orthologues: guinea pig NDRG4 (97% identical), mouse Ndrg4 (96% identical), pig NDRG4 (94% identical), rat Ndrg4 (93% identical), tropical clawed frog ndrg4 (85% identical), zebrafish ndrg4 (85% identical), macaque NDRG4 (84% identical), dog NDRG4 (72% identical), rabbit NDRG4 (69% identical), chimpanzee NDRG4 (64% identical), Drosophila melanogaster MESK2 (40% identical), Caenorhabditis elegans Y48G10A.3 (29% identical), and 2 more. Paralogues in human: NDRG3 (63% identical), NDRG2 (62% identical), NDRG1 (61% identical).
Diseases named in the same sentence as NDRG4 in open-access papers:
NDRG4 is named in the same sentence as 48 diseases in open-access papers, as found by Europe PMC text mining. Sharing a sentence is not in itself a finding about the gene and the disease. The quoted sentences say what the papers report.
colorectal cancer (27 papers, 2014 to 2025). A primary or metastatic malignant neoplasm that affects the colon or rectum. "Analysis of the methylation status of the TFPI2 and NDRG4 genes in peripheral blood mononuclear cells has demonstrated high diagnostic potential, as both genes are hypermethylated in colorectal cancer." (PMID 40867261, 2025). "Here, we developed the ColoCaller test, which simultaneously detects the methylation status of the SDC2, TFPI2, WIF1, and NDRG4 genes in stool DNA, to optimize the screening of gastric and colorectal cancer in high-risk populations." (PMID 35419280, 2022). "In the present study, we found a significant stratifying impact of NDRG4 on the association between obesity and clinical outcome in colorectal cancer." (PMID 26515606, 2016). "A statistically significant association between poor overall survival and reduced NDRG4 mRNA expression level was found in patients with colorectal cancer." (PMID 26515606, 2016). "We conducted the present study to determine NDRG4 protein expression pattern and its association with colorectal cancer carcinogenesis, progression, prognosis and PI3K-AKT activity." (PMID 25749388, 2015). "Given the strong association between NDRG4 and colorectal cancer differentiation, invasion and metastasis, we further investigate its prognostic role utilized the cut-off point of positive and negative staining of NDRG4." (PMID 25749388, 2015). "To understand the role of NDRG4 in colorectal cancer and to determine the potential functional mechanism, we began by investigating NDRG4 expression in clinical specimens and its association with clinicopathological characteristics as well as p-AKT." (PMID 25749388, 2015). "Given the close association found between NDRG4 and colorectal cancer progression, we further investigated its prognostic role in two separate cohorts." (PMID 25749388, 2015). "To clarify the role of NDRG4 in colorectal cancer, we investigated the association of NDRG4 staining with clinicopathological characteristics in both study cohorts." (PMID 25749388, 2015). "To detect the role of NDRG4 in colorectal cancer, we next examined the association of NDRG4 with clinicopathological characteristics in both study cohorts." (PMID 25749388, 2015). "This is the first direct evidence of the association between NDRG4 and clinicopathological characteristics of clinical colorectal cancer." (PMID 25749388, 2015). "To test this hypothesis, we investigated whether the associations of obesity with prognosis of colorectal cancer would be modified according to NDRG4 expression status in the present study." (PMID 26515606, 2016). "Thus, considering the potential significant interaction between NDRG4 and obesity of patients with colorectal cancer, we examined the association of obesity with disease-free in strata of NDRG4 expression." (PMID 26515606, 2016). "In the present study, we investigated whether NDRG4 status could modify the association of obesity with clinical outcome of colorectal cancer." (PMID 26515606, 2016). "Our retrospective and prospective investigation indicated for the first time that NDRG4 protein could be an independent prognostic predictor to identify high risk colorectal cancer patients." (PMID 25749388, 2015). "In addition, we also investigated critical molecular events such as KRAS, BRAF and PIK3CA mutations and MSI, all of which have been associated with colorectal cancer prognosis to justify the independent prognostic role of NDRG4." (PMID 25749388, 2015). "Therefore, high risk colorectal cancer patients could be better identified based on the combination of NDRG4 and PI3K-AKT activity." (PMID 25749388, 2015). "NDRG4 is usually expressed in heart and brain cells, and has been recently found to be downregulated in colorectal cancer as a result of promotor hypermethylation." (PMID 34385566, 2021).
colorectal cancer (continued). "The N-Myc downstream-regulated gene 4 (NDRG4) plays a role in cell growth and differentiation and is a putative tumor suppressor shown to be downregulated in colorectal cancer." (PMID 33030559, 2021). "The strong clinical potential of the platform has also been confirmed through a study of the tumor suppressor gene NDRG4, which has been found to be methylated in colorectal cancer." (PMID 34577737, 2021). "Three out of four colorectal cancer-positive patients were positive for NDRG4 methylation by using the HYPER-Melt platform, while only one of the four healthy volunteers tested positive." (PMID 34577737, 2021). "NDRG4 was also reported as a potential biomarker for colorectal cancer, detected in fecal DNA methylation profiles." (PMID 32927604, 2020). "Cologuard (indicated for colorectal cancer screening) is a kit that includes a molecular analysis for DNA mutations (such as KRAS mutation), methylation biomarkers such as BMP3 and NDRG4 methylation, and an immunochemical assay for human hemoglobin." (PMID 33114412, 2020). "Along these lines, NDRG4 methylation has emerged as a useful DNA methylation marker, in combination with other markers, for colorectal cancers." (PMID 32927604, 2020). "Limited studies on NDRG3 and NDRG4 revealed that NDRG4 plays tumor suppressive roles in colorectal cancer and glioblastoma." (PMID 30413609, 2018). "NDRG4 acts as a candidate tumor suppressor gene whose expression is frequently repressed by its promoter methylation in colorectal cancer." (PMID 28042954, 2017). "NDRG4 mRNA expression in colorectal cancer was significantly decreased compared with that in adjacent normal specimens and noncancerous control mucosa samples (P < 0.001)." (PMID 26515606, 2016). "We have recently demonstrated that NDRG4 protein expression was significantly decreased during carcinogenesis process of colorectal cancer." (PMID 26515606, 2016). "Kaplan-Meier analysis for postoperative overall survival showed that patients with colorectal cancer of preserved NDRG4 expression had longer overall survival compared with patients with reduced expression of NDRG4 (log-rank test: P < 0.001)." (PMID 26515606, 2016). "Kaplan-Meier analysis was used to evaluate the disease-free survival of patients with colorectal cancer and NDRG4 mRNA expression." (PMID 26515606, 2016). "Univariate survival analysis showed that obese patients with colorectal cancer of reduced NDRG4 expression had unfavorable overall survival compared with nonobese patients (log-rank test: P = 0.020)." (PMID 26515606, 2016). "In conclusion, to our knowledge, this is the first study to describe the function of NDRG4 protein in carcinogenesis, progression and prognosis of colorectal cancer." (PMID 25749388, 2015). "Results showed a statistically significant decrease of NDRG4 expression from normal mucosa, chronic colitis, ulcerative colitis, atypical hyperplasia to colorectal cancer." (PMID 25749388, 2015). "Results showed that NDRG4 protein expression was significantly decreased from normal mucosa, chronic colitis, ulcerative colitis, atypical hyperplasia to colorectal cancer." (PMID 25749388, 2015). "In the present study, we investigated the NDRG4 protein expression and its role in colorectal cancer carcinogenesis, progression and prognosis, as well the association of NDRG4 with PI3K-AKT activity." (PMID 25749388, 2015). "We investigated the role of NDRG4 protein in colorectal cancer and its prognostic value in a hospital-based retrospective training cohort of 272 patients and a prospective validation cohort of 708 patients were." (PMID 25749388, 2015). "The sensitivity and specificity of methylated NDRG4 gene expression for us as a biomarker in colorectal cancer was analyzed and compared with 16 age-matched healthy controls." (PMID 25663916, 2015). "The present study explored the use of methylated NDRG4 gene as a candidate biomarker for diagnosis of colorectal cancer (CRC)." (PMID 25663916, 2015).
colorectal cancer (continued). "Overexpression of NDRG4 in colorectal cancer cell can significantly suppress PI3K-AKT activity, even after EGF stimulation." (PMID 25749388, 2015). "On the other hand, NDRG4 plays a tumor suppressive role in glioblastoma and colorectal cancer." (PMID 40378957, 2025). "Limited studies on NDRG4 indicate that it may function as a tumor suppressor in multiple cancer types, including breast cancer, esophageal adenocarcinoma, colorectal cancer, and pancreatic cancer." (PMID 40378957, 2025). "Similarly, multi-target stool DNA tests involving methylation detection of NDRG4 in combination with BMP3 or SDC2 in the diagnosis of colorectal cancer have the sensitivities ranging from 85%-98% and specificity ranging from 86.6%-90% 32, 46-50." (PMID 33391430, 2021). "DNA hypermethylation of NDRG4 was frequently detected in colorectal cancers." (PMID 32927604, 2020). "Besides the role of NDRG4 in colorectal cancer, NDRG4 and the other NDRGs have also been described to be involved in nervous system cancers, like meningioma, neuroblastoma, and glioma." (PMID 31485792, 2019). "The aim of this study was to probe the methylation status of SEPT9, BMP3, NDRG4, and SDC2 in stool and study whether methylation of these genes is associated with colorectal cancer." (PMID 31602277, 2019). "We previously identified NDRG4 promoter methylation as a biomarker for the detection of colorectal cancer, and we observed that NDRG4 is specifically expressed in neuronal cell bodies and nerve fibers in the intrinsic nervous system of the gut: the enteric nervous system (ENS)." (PMID 31485792, 2019). "Previous NDRG4 methylation studies were mainly involved in colorectal cancer and pancreatic cancer." (PMID 28042954, 2017). "In addition, NDRG4 in colorectal cancer was negatively correlated with PI3K/AKT activity and can significantly inhibit PI3K/AKT activity in tumor cell." (PMID 26515606, 2016). "A recent comparative study on multitarget stool DNA test for colorectal cancer screening also showed that aberrant NDRG4 methylation was more likely to be detected in cancers, which further surport our results on the tumor suppressive role of NDRG4 in colorectal cancer." (PMID 26515606, 2016). "And the activity of PI3K/AKT signaling in colorectal cancer can be effectly attenuated by NDRG4." (PMID 26515606, 2016). "As investigation on disease-free survival demonstrated that in only reduced NDRG4 group, not preserved NDRG4 group, obese patients with colorectal cancer had higher risk of tumor relapse compared with those nonobese patients." (PMID 26515606, 2016). "Moreover, our investigation revealed that the prognostic impact of obesity on colorectal cancer relapse and overall mortility was significantly stratified by NDRG4 mRNA expression level." (PMID 26515606, 2016). "Threrfore, it is possibile that the prognostic value of obesity in colorectal cancer might differ according to NDRG4 status." (PMID 26515606, 2016). "In summary, our large cohort propective study demonstrated that mRNA expression levels of NDRG4 in primary colorectal cancer might be a powerful, independent predictor of disease relapse and prognosis." (PMID 26515606, 2016). "As normalized to 18s rRNA, the RQ (standing for relative expression obtained by 2−ΔΔCt method) of NDRG4 mRNA in colorectal cancer samples was 1.12 ± 0.15 (mean ± SD), while the relative NDRG4 mRNA expression detected in matched adjacent normal tissues was 1.87 ± 0.21." (PMID 26515606, 2016). "Therefore, 160 cases of colorectal cancer were defined as reduced NDRG4 expression group while 66 cases were defined as preserved expression group." (PMID 26515606, 2016). "However, we have demonstrated that NDRG4 protein expression was significantly decreased from normal mucosa, chronic colitis, ulcerative colitis, atypical hyperplasia to colorectal cancer tissues." (PMID 26515606, 2016).
colorectal cancer (continued). "However, a recent study found that the prevalence of NDRG4 promoter methylation was increased in colorectal cancer." (PMID 25749388, 2015). "However NDRG4 also been identified as a tumor suppressor gene with NDRG4 overexpression resulting in decreased colorectal cancer cell proliferation and invasion." (PMID 26053091, 2015). "This promoter methylation pattern suggested that NDRG4 might play an important role within colorectal cancer carcinogenesis and progression." (PMID 25749388, 2015). "As NDRG4 is more than 60% identical in amino acid sequence to NDRG2, this sequence similarity suggests NDRG4 may recapitulate the tumor suppressive function of NDRG2 in colorectal cancer." (PMID 25749388, 2015). "However, in contrast, the present study together with our previous work indicated that NDRG4 and NDRG2 protein expression was both decreased in colorectal cancer and similar had association with clinicopathological characteristics and prognosis." (PMID 25749388, 2015). "As it was proved that the cut-off point of NDRG4 staining utilized in retrospective study could effectively stratify colorectal cancer prognosis, we further recruited a prospective study cohort including 708 patients to validate its predictive role." (PMID 25749388, 2015). "Methylated NDRG4 gene expression from colorectal carcinoma tissue, paracarcinoma tissues, stools, blood and urine were detected successfully in DNA samples from 84 patients, by nested methylation-specific polymerase chain reaction and denaturing high-performance liquid chromatography." (PMID 25663916, 2015). "However, in gastrointestinal tract tumors, current evidences demonstrated that NDRG4 is downregulated in gastric cancers and colorectal cancers, suggesting that it may function as a tumor suppressor." (PMID 32927604, 2020). "Because NDRG4 methylation has been reported in colorectal cancers and our screening data showed downregulation of NDRG4 expression that was reversed following 5-Aza treatment, we hypothesized that NDRG4 promoter DNA hypermethylation may be the major mechanism to silence NDRG4 in EAC." (PMID 32927604, 2020). "While DNA methylation in genes MDF1, SSTR2, CMTM3, TGFB2, and NDRG4 is a potential marker for the detection of colorectal cancer in the early stages of its development, hypermetylation in gene CLDN11 is associated with metastasis and poor prospect of patient survival with colorectal cancer." (PMID 32370233, 2020). "The biological function of NDRG4 is largely unknown in colorectal cancer until now." (PMID 26515606, 2016). "Considering the significant role of PI3K/AKT signaling in carcinogenesis and energy metabolism, we tested the hypothesis that NDRG4 expression levle in colorectal cancer might correlate to patient's energy metabolism and modify tumor cell malignant behavior in the present study." (PMID 26515606, 2016). "Thus, we speculate that NDRG4 might possess a tumor suppressor role in tumor carcinogenesis, invasion and metastasis of colorectal cancer by its interaction with PI3K-AKT signal." (PMID 25749388, 2015). "Thus, inflammation related signals might be the target of NDRG4 during colorectal cancer carcinogenesis and progression." (PMID 25749388, 2015). "DNA methylation biomarkers for colorectal cancer, such as SEPT9, NDRG4 and BMP3, which have received FDA approval for blood- or stool-based CRC screening, have been validated." (PMID 41291100, 2025). "For example, in the United States, hypermethylation in the promoter regions of BMP3, NDRG4, SEPT9, and VIM genes have been approved for colorectal cancer screening." (PMID 36831050, 2023). "For colorectal cancer screening, a methylation marker panel consisting of bone morphogenic protein 3 gene (BMP3) and NDRG family member 4 gene (NDRG4) has been developed and validated in multi-prospective screening trials." (PMID 36765573, 2023).